TBX15 (T-box transcription factor 15)
Diseases named in the same sentence as TBX15 in open-access papers (continued):
Sharing a sentence is not in itself a finding about the gene and the disease.
thyroid cancer (5 papers, 2016 to 2023). "Recent research has discovered that TBX15 promotes cancer progression in solid tumors such as thyroid cancer, renal clear cell carcinoma, and ovarian cancer, but few studies have reported its biological behavior and molecular mechanism in glioma." (PMID 37328486, 2023). "In thyroid cancer cells, three putative NF-κB matching sites were found in a 600-bp segment of TBX15's 5'flanking region, in response to the ectopic expression of TNF-α or NF-κBp656." (PMID 37328486, 2023). "TBX15 acts as an anti-apoptotic factor in thyroid cancer by inhibiting the expression of proapoptotic BAX and increasing the expression of antiapoptotic BCL2 and BCL-XL regulators." (PMID 33447348, 2020). "More recently, we have shown an antiapoptotic role of TBX15, together with its altered expression in thyroid cancer cells." (PMID 27327083, 2016). "Bisulphite sequencing of this CpG island, position -3852 bp to -3381bp of the TBX15 gene, was performed in HeLa cells and six thyroid cancer cell lines (TPC-1, BCPAP, WRO, CGTH, FRO and 8305)." (PMID 27327083, 2016). "To investigate if NF-κB was involved in the regulation of TBX15 expression we stimulated HeLa cells and three thyroid cancer cell lines with TNF-α to activate NF-κB, and subsequently we measured the TBX15 mRNA levels." (PMID 27327083, 2016). "Several genes that were previously shown to contribute to aggressive phenotypes in thyroid cancer, including SERPINE1 and TBX15, were identified in this module and significantly correlated with LNM." (PMID 36231143, 2022). "Of importance, we found that TBX15 mRNA expression was increased in response to TNF-α in HeLa and three thyroid cancer cell lines; moreover, the analysis of the TBX15 expression in p65-/- MEF cells stimulated with TNF-α indicated that the effect was mediated by NF-κB." (PMID 27327083, 2016).
glioma (4 papers, 2023 to 2024). A benign or malignant brain and spinal cord tumor that arises from glial cells (astrocytes, oligodendrocytes, ependymal cells). "TBX15 expression was increased in human gliomas and associated with worse clinicopathological characteristics and poorer survival prognosis in glioma patients." (PMID 37328486, 2023). "It was found that TBX15 expression was remarkably up-regulated in a spectrum of malignancies including glioma, and TBX15 upregulation was associated with poor prognosis of glioma patients." (PMID 37328486, 2023). "We also discovered that elevation of TBX15 expression in glioma was associated with a poor prognosis." (PMID 37328486, 2023). "TBX15 was suggested to be associated with immune cell infiltration and immunosuppression and exhibit poor clinicopathological characteristics and survival prognosis in glioma patients." (PMID 38762464, 2024). "TBX15 mRNA and protein expressions in glioma cells and adjacent normal tissue were detected and compared by RT-qPCR and Western blot." (PMID 37328486, 2023). "The present study aimed to evaluate the expression of TBX15 in gliomas in TCGA, and GTEx cohorts, and investigate its potential mechanisms." (PMID 37328486, 2023). "In this study, we intended to explore the prognostic value of TBX15 and its link to glioma immune infiltration and examine TBX15 expression in pan-cancer using RNAseq data in TPM format from TCGA and GTEx." (PMID 37328486, 2023). "The correlation between TBX15 upregulation and the clinicopathological characteristics of glioma patients was assessed by using TCGA databases, and the relationship between TBX15 and other genes in glioma was evaluated by using TCGA data." (PMID 37328486, 2023). "Our results demonstrated that TBX15 was highly expressed in gliomas and cell lines, working as an oncogenic protein." (PMID 37328486, 2023). "It was found that TBX15 mRNA expression in glioma tissues was significantly higher than that in the adjacent normal tissues, and this difference was most obvious in high-grade gliomas." (PMID 37328486, 2023). "In conclusion, TBX15 played an important role in immune cell infiltration in glioma and may prove to be a predictor of the prognosis in glioma patients." (PMID 37328486, 2023). "In addition, TBX15 was highly expressed in gliomas in the GSE16011." (PMID 37328486, 2023). "However, the prognostic value of TBX15 in glioma and its relationship with immune infiltration remain unknown." (PMID 37328486, 2023). "Finally, TBX15 may play a role in immune cell infiltration, which may serve as an indicator to forecast the prognosis of glioma patients." (PMID 37328486, 2023).
hepatocellular carcinoma (4 papers, 2017 to 2024). A malignant tumor that arises from hepatocytes. "Aberrant TBX15 methylation has been described in various tumors, such as prostate, ovarian, and hepatocellular carcinomas." (PMID 38971778, 2024). "We analyzed DNA methylation profiles of hepatocellular carcinoma (HCC), and investigated the clinical role of most heypermethylated of tumor, encodes T-box 15 (TBX15), which was originally involved in mesodermal differentiation." (PMID 33447348, 2020). "Recently, genome-wide DNA methylation analysis suggested that TBX15 was hyper-methylated and down-expressed in hepatocellular carcinoma datasets." (PMID 28036274, 2017).
diabetes (3 papers, 2015 to 2023). "The TBX15 gene is involved in adipocyte differentiation, triglyceride accumulation, and mitochondrial function, and some of its variants reportedly increase the risk of diabetes and metabolic disease." (PMID 26418247, 2015). "Differential expression of Tbx15 between fat depots plays an important role in the interdepot differences in adipocyte differentiation, triglyceride accumulation, and mitochondrial function, which may contribute to the risk of diabetes and metabolic diseases." (PMID 29755575, 2018).
lung cancer (3 papers, 2018 to 2024). A malignant neoplasm involving the lung. "Recent studies indicated that both strands of miR-4732-5p and miR-4732-3p prevented lung cancer aggressiveness through inhibited TBX15/TNFSF11 axis or PI3K/Akt/GSK3β/Snail pathway." (PMID 39337462, 2024).
clear cell renal cell carcinoma (2 papers, 2021 to 2022). "In addition, miR-212-5p expression is also reduced in renal clear cell carcinoma (RCC), and miR-212-5p overexpression blocks the migration, invasion, and proliferation of RCC cells by targeting TBX15." (PMID 35892080, 2022).
male pattern baldness (2 papers, 2023). "The 2 prioritized genes on chromosome 1, TBX15 and WARS2, were associated with similar phenotypes, including male pattern baldness, white blood cells, measures of overall adiposity and its distribution, bone mineral density, and height." (PMID 37889180, 2023).
Blepharophimosis (1 paper, 2004). A fixed reduction in the vertical distance between the upper and lower eyelids with short palpebral fissures. "The deH phenotype exhibits little overlap with these features; instead, we suggest a more likely candidate for mutations of human TBX15 would be frontofacionasal syndrome, an unmapped autosomal recessive condition characterized by brachycephaly, blepharophimosis, and midface hypoplasia." (PMID 14737183, 2004).
dilated cardiomyopathy (1 paper, 2023). Cardiomyopathy which is characterized by dilation and contractile dysfunction of the left and right ventricles. "Here, we show that lysine demethylase 8 (Kdm8) maintains an active mitochondrial gene network by repressing Tbx15, thus preventing dilated cardiomyopathy leading to lethal heart failure." (PMID 38665902, 2023). "NAD+ supplementation prevented dilated cardiomyopathy in Kdm8 mutant mice, and TBX15 overexpression blunted NAD+-activated cardiomyocyte respiration." (PMID 38665902, 2023). "In humans, KDM8 was downregulated in hearts affected by dilated cardiomyopathy, and higher TBX15 expression correlated with the strongest downregulation of genes encoding mitochondrial proteins." (PMID 38665902, 2023). "Furthermore, KDM8 was downregulated in human hearts affected by dilated cardiomyopathy, and higher TBX15 expression defines a subgroup of affected hearts with the strongest downregulation of genes encoding mitochondrial proteins." (PMID 38665902, 2023). "Deletion of Kdm8 in mouse cardiomyocytes increased H3K36me2 with activation of Tbx15 and repression of target genes in the NAD+ pathway before dilated cardiomyopathy initiated." (PMID 38665902, 2023).
fibrosarcoma (1 paper, 2017). A malignant mesenchymal fibroblastic neoplasm affecting the soft tissue and bone. "In this study, the overexpression of TBX15 in the fibrosarcoma cell line HT-1080 increased cell proliferation, suggesting oncogenic function of TBX15 in DFSP." (PMID 28977029, 2017). "To investigate oncogenic function of TBX15 in DFSP, we performed an in vitro experiment using the fibrosarcoma cell line HT-1080." (PMID 28977029, 2017).
Glucose intolerance (1 paper, 2015). Glucose intolerance (GI) can be defined as dysglycemia that comprises both prediabetes and diabetes. "Heterozygous deletion in mice (Tbx15+/−) results in a milder shift in fibre type, increased adiposity and glucose intolerance." (PMID 26299309, 2015).
gynecological cancers (1 paper, 2019). "Whether AMPD3/NRN1/TBX15 methylations may occur in other gynecological cancers or in benign tumors remains to be determined." (PMID 31775891, 2019).
heart failure (1 paper, 2023). Inability of the heart to pump blood at an adequate rate to meet tissue metabolic requirements. "Altogether, our results suggest that KDM8 epigenetically controls cardiac metabolism repressing TBX15 to prevent the initiation of cardiac deterioration toward heart failure." (PMID 38665902, 2023). "Furthermore, higher expression of TBX15 defines a group of DCM-affected hearts with the strongest repression of metabolic gene networks, linking KDM8 and TBX15 with heart failure." (PMID 38665902, 2023). "Our findings open the possibility that TBX15 or its downstream targets and metabolic pathways could be modulated to prevent cardiac metabolism derangement and heart failure." (PMID 38665902, 2023). "Dysregulation of TBX15-controlled gene expression could be relevant in human heart failure." (PMID 38665902, 2023).
Hirsutism (1 paper, 2018). Abnormally increased hair growth referring to a male pattern of body hair (androgenic hair). "In addition to validation of SNPs associated with these previous traits, our study identified three novel hirsutism loci that were also eQTLs for BCL2, GCC2 and LIMS1, and TBX15." (PMID 29895819, 2018).
inclusion body myositis (1 paper, 2022). A slowly progressive degenerative inflammatory disorder of skeletal muscles characterized by late onset weakness of specific muscles and distinctive histopathological features. "Another complicating factor is that Myoblast 8 was derived from a 74-y patient with inclusion-body myositis so that the disease state might have influenced TBX15 DNA methylation." (PMID 36547252, 2022).
melanoma (1 paper, 2022). A malignant, usually aggressive tumor composed of atypical, neoplastic melanocytes. "Both SOX10 and TBX15 were correlated with the unfavourable prognosis of melanoma patients, and SOX10 positively correlates with SMARCA4." (PMID 36317703, 2022). "Pearson regression results from 4 different melanoma databases showed that SOX10 and USF2 were positively correlated with the expression of SMARCA4, yet TBX15 and ETS2 were negatively correlated with the expression of SMARCA4." (PMID 36317703, 2022).
meningioma (1 paper, 2023). A generally slow growing tumor attached to the dura mater. "Interestingly, seven of the meningioma-associated antigens were shared between all WHO grades (NMA2, TBX15/18, XXLT1, SLC25A44, RHOD, CREBL2, and PLCD4)." (PMID 37368072, 2023).
renal cell carcinoma (1 paper, 2022). "MiR-212 inhibits cell proliferation, migration, and invasion in renal cell carcinoma (RCC) and exerts tumor suppressor effects by downregulating T-box transcription factor TBX15 (TBX15)." (PMID 35326471, 2022).
sarcopenia (1 paper, 2022). Progressive decline in muscle mass due to aging which results in decreased functional capacity of muscles. "Because myofiber type plays major and complex roles in muscle performance, muscle formation, muscle repair, and sarcopenia, the epigenetic regulation of postnatal TBX15 expression is likely to be important for normal muscle function and maintenance." (PMID 36547252, 2022).
thyroid (1 paper, 2023). "NF-κBp65 directly interacted with the 5' distal regulatory domain of TBX15 as a regulatory element of TBX15 to boost TBX15 mRNA production in thyroid cancerous cells." (PMID 37328486, 2023).
triple-negative breast carcinoma (1 paper, 2025). An invasive breast carcinoma which is negative for expression of estrogen receptor (ER), progesterone receptor (PR), and human epidermal growth factor receptor 2 (HER2). "Indeed, methylation of another member of T-Box transcription factors, TBX15, was detected in triple-negative breast cancer as compared to non-triple-negative breast cancer, suggesting that it might be involved in the non-responsiveness to hormonal therapy." (PMID 40001874, 2025).
type 2 diabetes (1 paper, 2024). "In humans, TBX15 expression in omental fat negatively correlates with waist-to-hip ratio, a proxy for propensity for type 2 diabetes." (PMID 39401200, 2024).
cancer (18 papers, 2015 to 2025). A tumor composed of atypical neoplastic, often pleomorphic cells that invade other tissues. "TBX15 was initially identified as one of genes associated with genome-wide DNA methylation in several types of cancer tissues." (PMID 34663310, 2021). "In cancer cells, TBX15 impacts apoptosis which represents a hallmark for HL." (PMID 33539429, 2021). "In cancer, TBX15 expression appears to be stimulated by NF-kB, exerting an anti-apoptotic effect and promoting cell proliferation." (PMID 37987361, 2023). "To understand new mechanism of chemoresistance, we found that decreased expression of the transcription factor, TBX15 was associated with DOX resistance through regulating autophagy and glycolysis in cancer cells." (PMID 34663310, 2021). "The expression of T-box transcription factor 15 (TBX-15) was found downregulated in some cancer tissues." (PMID 34663310, 2021). "Together, the present and previous findings support the importance of conducting further investigations to determine the role of TBX15 in cancer, particularly in tumor progression." (PMID 33447348, 2020). "Further study is still needed to discover the true mechanism for tumor malignancy of TBX15 focused on ROS concentration and its signaling pathway in each cancer." (PMID 33447348, 2020). "Those issues should be solved in several cancers, to clarify the true function of TBX15 for tumor malignancy in each cancer." (PMID 33447348, 2020). "TBX15 mRNA expression in tumor tissue was varied according to type of carcinoma, while it was significantly lower in tumor tissue of HCC compared to nontumor tissue." (PMID 33447348, 2020). "Recent studies found that TBX15 has an antiapoptotic role and its expression is altered in cancer cells, indicating a role for TBX15 in cell proliferation and carcinogenesis." (PMID 28977029, 2017). "Recently we found that TBX15 has an antiapoptotic role and its expression was altered in cancer cells." (PMID 27327083, 2016). "We identified a NF-κB responsive region with a positive effect in the transcription of TBX15 in human cancer cells." (PMID 27327083, 2016). "Among the highly up-regulated genes, TBX15 showed the strongest hypermethylation across all cancer entities (median = 0.228)." (PMID 27876760, 2016). "A relevant issue in the present study is the link between TBX15 and NF-κB, and this novel discovery would be important in development and cancer processes." (PMID 27327083, 2016). "Based on these data and taking into account that NF-κB is an important factor in cancer, we considered NF-κB as a potentially relevant factor to regulate TBX15 transcription." (PMID 27327083, 2016). "So, further investigation is warranted to understand the role of TBX15 in cancer and development processes, and in relation to NF-κB." (PMID 27327083, 2016). "In summary, we provide novel data showing that NF-κB signaling up-regulates TBX15 expression in cancer cells." (PMID 27327083, 2016). "We also found a significant response of TBX15 to TNF-α activation of the NF-κB pathway using five cancer cell lines, and similar results were obtained when NF-κB was activated with PMA/ionomycin." (PMID 27327083, 2016). "Additionally, TNF-α induced activation of NF-κB enhances the expression of TBX15 mRNA in cancer cells." (PMID 39286028, 2024). "It was reported that the NF-κB signaling pathway upregulates TBX15 expression in cancer cells." (PMID 37328486, 2023). "In cancer cell lines, human TBX15 was shown to have an anti-apoptotic function that could be partly mediated by its suppression of transcription of several apoptosis-associated BCL2 family genes." (PMID 36547252, 2022). "We found RNA-seq and methylome data for one cancer cell line that expressed TBX15." (PMID 36547252, 2022). "TBX15 belongs to a family of transcription factors regulating differentiation, proliferation, tissue integrity and epithelial-mesenchymal transition, which are relevant to cancer development and metastasis." (PMID 34021172, 2021).